CRP (C-reactive protein)
Diseases named in the same sentence as CRP in open-access papers (continued):
Sharing a sentence is not in itself a finding about the gene and the disease.
Cachexia (continued). "The main findings of this study were that daily supplementation with copaiba oleoresin improved cirrhosis-associated cachexia by increasing weight gain and body fat while also reducing systemic inflammation, as evidenced by decreased circulating CRP levels and liver oxidative stress." (PMID 39596809, 2024). "Cancer cachexia is a multifactorial syndrome causing progressive skeletal muscle loss leading to progressive functional deterioration and is associated with increased production of CRP, reduced albumin, and a worse performance status (lower AKPS)." (PMID 39628313, 2024). "Therefore, cachexia is closely associated with unfavorable prognostic variables found in the current study, including high PS, low albumin level, high CRP, and low BMI." (PMID 38438534, 2024). "CRP was previously claimed to associate with survival and cachexia among patients with PDAC." (PMID 35740504, 2022). "This aspect appears crucial for physicians considering that adipose tissue changes may occur in the early stage of cachexia even when body weight loss and inflammatory status (e.g. increased CRP levels) is minimal." (PMID 34939367, 2022). "Cancer-related cachexia or weight loss associates with various biomarkers of systemic inflammation, including but not limited to, select cytokines (e.g., interleukin (IL)–6 and IL-8) and C-reactive protein (CRP) concentrations." (PMID 32371869, 2020). "Additionally, the authors proposed that cachexia-associated systemic inflammation, as indicated by increased CRP levels, may decrease CYP3A4 levels by downregulating its expression, possibly leading to increased plasma fentanyl concentrations." (PMID 39272951, 2024). "Usually, diagnostic tools for cachexia include loss of weight and lean body mass, fatigue, anorexia, reduced physical performance (for example, total activity or 6-min walk distance) and biochemical abnormalities of c-reactive protein (CRP), albumin, and protein." (PMID 28193264, 2017). "Also, it is reported that CRP is associated with the nutrition status and development of cachexia." (PMID 24130817, 2013). "Our results may support the association of CRP concentrations and cancer related cachexia." (PMID 20920199, 2010). "The authors propose an objectively measured laboratory cachexia score (LCAS) which combines systemic inflammation as measured by the widely validated mGPS (a CRP and albumin-based score) and metabolic dysfunction as measured by LDH." (PMID 40133911, 2025). "A total of 168 patients were categorized into four groups based on cachexia and C-reactive protein (CRP) levels." (PMID 41294682, 2025). "In both humans and mice with cancer, cachexia correlates with elevated markers of chronic inflammation, including C-reactive protein (CRP) and cytokines such as tumor necrosis factor-alpha (TNF-α), interleukin-1 (IL-1), and IL-619." (PMID 41278737, 2025). "When cachexia status was classified using a 4-stage system 32, we find that patients with PCa can be differentiated from NCa patients by CRP, TIMP-1 and GDF-15." (PMID 39989973, 2025). "NLR, PLR, SII, TNFα, IL-6, IL-8, and CRP correlated positively to cachexia and albumin while Hb and lymphocyte count correlated negatively to cachexia." (PMID 38744744, 2024). "Regarding cachexia status, most studies define cachexia using percentage weight loss (2% or 5% weight loss), and have demonstrated that cachexia correlated to WBC, CRP, and NLR." (PMID 38744744, 2024). "We constructed an inflammatory biomarker‐based cachexia model using well‐established systemic inflammatory markers, such as CRP, NLR, ALB and GPS, based on previous studies, and compared their diagnostic performance." (PMID 39192568, 2024). "Patients with cachexia had higher rates of prolonged length of hospital stay (P < 0.001), inflammation (CRP, P < 0.001), poor nutrition (PG‐SGA, P < 0.001), reduced quality of life (P < 0.001) and increased hospital expenses (P < 0.001)." (PMID 39192568, 2024).
Cachexia (continued). "Inflammatory cytokines in cachexia induce CRP production and inhibit Alb synthesis, which are positive and negative hepatic acute-phase proteins, respectively." (PMID 39272951, 2024). "Albumin, NLR, Hb, PLR, SII, TNFα, IL-8, and CRP were reliable indicators of QoL, appetite, and cachexia." (PMID 38744744, 2024). "Thirty-two patients (32%) with cachexia met the criteria of both low serum Alb levels (Alb < 3.3 g/dL) and high serum CRP levels (CRP > 1.9 mg/dL) in all patients." (PMID 38592548, 2024). "The median OS and PFS of cachexia patients with both low serum albumin levels and high serum CRP levels were 6.0 months and 0.93 months, respectively." (PMID 38592548, 2024). "Due to limited availability of inflammatory markers, such as CRP or ratios derived from a CBC with differential, we were unable to assess levels of systemic inflammation, a hallmark of cancer‐associated cachexia, between groups beyond serum albumin levels." (PMID 38123146, 2024). "In the cachexia group, the median levels were 173.1 pg/mL, 1.63 pg/mL, 51,255.8 pg/mL, and 110,010.3 pg/mL for ghrelin, CRP, PTX‐3, and OPN, respectively." (PMID 37712645, 2023). "ROC curve analysis suggested that a combination of choline and Trp predicts cachexia more successfully than CRP and albumin." (PMID 37803016, 2023). "Logistic regression analysis identified ghrelin, c‐reactive protein (CRP), pentraxin‐3 (PTX‐3), and osteopontin (OPN) as factors associated with cachexia." (PMID 37712645, 2023). "Analyzing the soluble immune mediators associated with cachexia, the combination of cachexia and PTX‐3 or OPN expression levels was predictive for PFS and the combination of cachexia and CRP or OPN expression levels was predictive for OS." (PMID 37712645, 2023). "CRP is one of many examples of acute phase reactant that are a byproduct of inflammation and have a relationship to cachexia." (PMID 38022578, 2023). "Second, C-reactive protein (CRP) is a classic marker of systemic inflammation included in Fearon definition of cachexia." (PMID 37629186, 2023). "In contrast, mGPS can predict the prognosis and evaluate the progression of cachexia based on CRP and albumin levels, which can classify cachexia stages." (PMID 37686634, 2023). "Cytokines that have been shown to impact on nutritional status in cachexia include C-reactive protein (CRP), tumour necrosis factor α (TNFα), interleukin (IL)-6 and IL-8 by triggering muscle wasting and negatively impacting survival in cancer." (PMID 37906352, 2023). "There were also significant differences in OS for the combination of cachexia and CRP (p = 0.038, log‐rank) or OPN (p < 0.001, log‐rank) expression levels, respectively." (PMID 37712645, 2023). "Concerning these parameters, an increase in CRP and reductions in hemoglobin and albumin as well as CHE were previously linked to cachexia." (PMID 31717736, 2019). "Patients in the cachectic group presented higher levels of CRP, characterizing the systemic inflammation which is typical of cachexia." (PMID 31466311, 2019). "C-reactive protein >10 mg/L and coinciding s-albumin <30 g/L was referred to as “laboratory cachexia”." (PMID 29534089, 2018). "As an example, high circulating levels of C-reactive protein (CRP) are frequently observed in cancer patients with cachexia." (PMID 26504362, 2015). "C-reactive protein, albumin, hemoglobin, and IL-6, biochemical markers of cachexia, were also evaluated." (PMID 26732354, 2015). "From the ongoing discussion, it appears that telmisartan is beneficial in controlling cachexia as evident from the improvement in cachexia markers namely, insulin, CRP, and IL-6." (PMID 24381940, 2013). "CRP (P<0.0001), albumin (P<0.0001) and haemoglobin (P<0.0001) were also significantly different among the cachexia groups." (PMID 21934689, 2011). "The three cachexia groups that were defined had also gradually higher CRP, lower albumin and lower haemoglobin levels." (PMID 21934689, 2011).
Cachexia (continued). "The values for C-reactive protein were significantly elevated in patients with cachexia (P = 0.002)." (PMID 19635171, 2009). "Finally, the elevation of CRP, one of the criteria for diagnosing cachexia, reflects the systemic inflammatory condition and has been reported in many diseases to be associated with impaired quality of life." (PMID 41220715, 2025). "Therefore, we further explored the predictive power of various inflammatory markers in cachexia patients and found that the CRP‐to‐albumin ratio (CAR) performed the best among these composite indices." (PMID 41216846, 2025). "Several studies have found that CRP and mGPS are indicators of cachexia." (PMID 39817619, 2025). "The diagnostic criteria for cachexia by the AWGC include weight loss, body mass index (BMI), and the presence of at least one of the following three symptoms: anorexia, decreased handgrip strength (HGS), or elevated levels of C-reactive protein (CRP)." (PMID 41220715, 2025). "Low Alb and high CRP levels are typical indicators of cachexia." (PMID 38592548, 2024). "Serum CRP level measurement is a useful marker in the diagnosis of cachexia." (PMID 38610941, 2024). "Compared with CRP‐based cachexia, their prognostic capabilities are remarkably similar." (PMID 39192568, 2024). "Group 3 could correspond to pre‐cachexia with loss of appetite; and group 4 to cachexia tending toward terminal cachexia (cytokine storm) with very high CRP." (PMID 38481033, 2024). "In clinical studies of cachexia, the acute phase response is synonymous with CRP." (PMID 38022578, 2023). "Multivariate analysis, adjusting for clinically significant factors, demonstrated that only high-sensitivity C-reactive protein (OR, 1.24; p = 0.04], the utilization of LDs (OR, 5.76; p = 0.03), and the presence of cachexia (OR, 2.53; p = 0.04) are independent predictors of anorexia." (PMID 40757528, 2023). "The combinations of cachexia and CRP, PTX‐3, or OPN might serve as predictors of survival in patients with NSCLC receiving immunotherapy." (PMID 37712645, 2023). "There was a significantly negative correlation betweenparameters generated by MF-BIA -PA and reactance- and C-reactive protein level-inflammatory marker used to diagnose cachexia (p < 0.01).This might relate to the occurrence of cachexia." (PMID 36342073, 2023). "In addition, both factors were associated with levels of different cytokines, namely CRP with interleukin-1β, a driver of MF pathogenesis, and albumin with TNF-α, a key mediator of cachexia." (PMID 36900271, 2023). "A placebo-controlled study in 128 GI cancer patients with cachexia indicated that fish oil-enriched nutritional support leads to lower C-reactive protein blood levels while increasing skeletal and lean muscle mass compared to the placebo group over 6 months of treatment." (PMID 37571328, 2023). "Similarly, using CSS scores, the current study found cachexia to be significantly related to CRP, IL-6, IL-8 and TNFα." (PMID 37906352, 2023). "CRP is an acute-phase protein known to be a marker of inflammation, and as previously established, its elevation is considered part of the symptom complex of cachexia." (PMID 37507961, 2023). "Pre‐treatment ghrelin, CRP, PTX‐3, and OPN may be associated with cachexia in NSCLC receiving PD‐1 inhibitors." (PMID 37712645, 2023). "However, in the multivariable analysis, only lean mass deficit and CRP were significant predictors of wasting syndrome (P < .05)." (PMID 35608430, 2022). "For the diagnosis of cachexia, we used serum hemoglobin, CRP, and albumin." (PMID 34630405, 2021). "The group with cachexia had higher CRP and lower fat_kg and Karnofsky scores." (PMID 34898583, 2021). "Furthermore, the inflammatory marker, C-reactive protein, is increased in patients suffering from cancer-cachexia." (PMID 32781663, 2020). "Patients with cachexia usually have a low SA and CRP values slightly above normal." (PMID 31388102, 2020).
Cachexia (continued). "Elevated CRP levels have also been reported in patients with cachexia and muscle wasting." (PMID 33291708, 2020). "While there are no specific laboratory markers for cachexia, it is commonly agreed that inflammatory parameters, including leukocyte count, CRP, and CHE as well as hemoglobin and albumin are associated with cachexia." (PMID 31717736, 2019). "Raised serum C-reactive protein (CRP), a biomarker for systemic inflammation, interleukin 6 (IL6), and growth differentiation factor-15 (GDF-15) are thought to be associated with cachexia." (PMID 31323984, 2019). "In the cachexia group, there were significantly more males (20/30) compared to the no/pre-cachexia group (6/16) and those patients who were cachectic had, as anticipated, significantly higher level of inflammation (measured by c-reactive protein (CRP))." (PMID 31816924, 2019). "Underlining this, our dropped out patients presented significantly higher CRP values and leucocyte counts, less serum albumin, total protein and low hemoglobin concentrations, indicating a higher inflammatory burden, disease severity and advanced cachexia." (PMID 30208857, 2018). "When instead looking at those who at some point fulfilled the criteria of laboratory cachexia and then continuously fulfilled the criteria in all available measurements from then on, N = 120, the median number of days from first found CRP >10 mg/L and coinciding s-alb <30 g/L was 47days." (PMID 29534089, 2018). "CRP>10mg/L and coinciding s-alb <30g/L will be referred to as “laboratory cachexia”." (PMID 29534089, 2018). "Increased CRP is supposed to be a valid laboratory and clinical marker in cachexia." (PMID 28193264, 2017). "Fearon and co-workers proposed that inclusion of a marker of systemic inflammation (e.g., CRP) in a cachexia stratification system could account for patients with real loss of function also perceiving themselves to have reduced function." (PMID 28193264, 2017). "With our present study, we were able to demonstrate slight but significant changes in quality of life in cachectic patients without using CRP as a diagnostic parameter for cachexia." (PMID 28193264, 2017). "In the blood samples, WBC counts were higher in the cachexia group (11,722 vs. 5,873/μL), as were CRP content (7.1 vs. 2.5 mg/dL), and serum IL-6 levels (40.2 vs. 13.0 pg/mL); however, the cachexia group’s albumin levels were lower (2.7 vs. 3.5 g/dL) than in the non-cachexia group." (PMID 25010770, 2014). "Finally, we examined the proposed cut-off values of CRP, hemoglobin and albumin for diagnosis of cachexia, in order to establish their clinical usefulness." (PMID 23294910, 2013). "Cancer cachexia was accompanied by signs of systemic inflammation, that is, elevated CRP and IL-6." (PMID 20407445, 2010). "More recently, the Asian Working Group for Cachexia (AWGC) has established criteria, defining cachexia as a weight loss > 2% over 3–6 months plus at least one of anorexia, reduced grip strength (< 28 kg for men and < 18 kg for women), or C-reactive protein (CRP) level of > 0.5 mg/dL." (PMID 40715550, 2025). "Thus, CRP appears to have the potential to identify patients with cancer-related cachexia." (PMID 39001427, 2024). "RFS‐1 was associated with cachexia (P = 0.002); RFS‐2, with higher CRP (P < 0.0001) and decreased physical function (P = 0.01); and RFS‐3 with better appetite (P = 0.04), lower CRP (P = 0.002), higher z‐SMI (P = 0.04) and z‐FMI (P < 0.0001), and less cachexia characteristics (all P < 0.001)." (PMID 38481033, 2024). "Pre‐treatment ghrelin, CRP, PTX‐3, and OPN expression levels may be associated with cachexia." (PMID 37712645, 2023). "We have shown that CRP and PTX3 may be associated with cachexia." (PMID 37712645, 2023). "We found that ghrelin, CRP, PTX‐3, and OPN expression levels may be associated with cachexia." (PMID 37712645, 2023). "Pre‐treatment ghrelin, CRP, PTX‐3, and OPN may be associated with cachexia." (PMID 37712645, 2023).
Cachexia (continued). "By integrating Cr and CAR (CRP/albumin) through a random forest model, the CCAR index simultaneously captures three key pathological dimensions of cachexia: inflammation, nutrition and metabolism." (PMID 41216846, 2025). "Tocilizumab demonstrated significant benefits in survival and various clinical parameters, including body weight, albumin, CRP, mGPS and symptom burden in patients with NSCLC and concurrent IL‐6‐elevated cachexia." (PMID 39523982, 2024). "Using CRP‐based cachexia as a reference, only the IBI‐based cachexia definition demonstrated positive clinical benefits (HR: 0.003, 95% CI: 0.005–0.006, P = 0.024)." (PMID 39192568, 2024). "In the investigation of relationships of QoL to biomarkers of cachexia, the results showed that albumin, NLR, Hb, PLR, SII, TNFα, IL-8, and CRP were all significantly related to QL-G, QL-FS, and QL-SS aspects of QoL assessment." (PMID 38744744, 2024). "Several clinical studies have reported that the concentration of C-reactive protein (CRP), a liver-derived acute-phase protein, correlates with the severity of cachexia and prognosis of cancer patients." (PMID 37803016, 2023). "Albumin and CRP concentration have been predictive of patient outcomes and serve as examples of APP that have clinical applicability to cachexia." (PMID 38022578, 2023). "Certain inflammatory mediators, such as C-reactive protein (CRP), IL-6, IL-1β, and TNF-α, play a pivotal role in initiating cachexia-induced muscle wasting." (PMID 37755304, 2023). "Since cachexia is associated with inflammation, and because activation of the complement system is a key feature of many inflammatory conditions, we further subdivided the cachexia group into patients with and without inflammation, as evidenced by elevated systemic CRP levels." (PMID 34830921, 2021). "Traditional inflammatory markers including C-reactive protein (CRP), tumor necrosis factor-alpha (TNF-α), and interleukin-6 (IL-6) remain valuable indicators of the systemic inflammation driving muscle wasting, particularly in cachexia." (PMID 41220691, 2025). "CRP levels of both cachectic patients without inflammation and patients without cachexia were significantly lower (3.8 [1.1–5.2] mg/L, P < 0.001, and 4.4 [1.2–8.3] mg/L, P = 0.001, respectively)." (PMID 38725139, 2024). "Ultimately, controlling systemic inflammation (i.e., lowering CRP levels) may reduce its impacts on the CNS and HPA axis, alleviate symptoms, and solve the cachexia-related complications." (PMID 39765960, 2024). "The literature supports significantly raised CRP (p = 0.020) and IL-6 (p = 0.040) for patients with cachexia compared to non-cachectic patients." (PMID 37906352, 2023). "Patients with NSCLC and cachexia who received PD‐1/L1 monotherapy tended to have worse survival than those without cachexia irrespective of presence of ghrelin, CRP, PTX‐3, and OPN." (PMID 37712645, 2023). "One challenge of examining the contribution of CRP to cachexia is that it is not synthesized in murine models of cachexia." (PMID 38022578, 2023). "Although confirmation of our data in further large‐scale studies is needed, given the small sample size in this study, our study showed that CRP, PTX‐3, and OPN expression levels might serve as prognostic factors in patients with cachexia." (PMID 37712645, 2023). "We also observed that patients with low CXI had a significantly higher level of serum CRP and IL-6 but a decreased level of serum prealbumin, indicating that low CXI could be a desirable measurement of cachexia." (PMID 36139560, 2022). "Finally, in the univariate analyses, the presence of lean mass deficit, CRP, and ESR predicted wasting syndrome (P < .05)." (PMID 35608430, 2022). "Nevertheless, its predictive value, in combination with other markers such as albumin, CRP, GDF‐15, or IL‐6, for instance, may represent an efficient signature for diagnosis of cachexia." (PMID 34427055, 2021).